LAMP1 (lysosome associated membrane protein 1)
Diseases named in the same sentence as LAMP1 in open-access papers (continued):
Sharing a sentence is not in itself a finding about the gene and the disease.
Pick disease (5 papers, 2019 to 2024). A rare neurodegenerative disorder leading to dementia. "In AD patients, as compared to patients with frontotemporal dementia, neuron-derived blood exosomes were found to have higher levels of lysosome-associated membrane protein 1 (LAMP1) and cathepsin D." (PMID 38887492, 2024). "LAMP-1 shuttles between lysosomes, endosomes, and the plasma membrane and binds to cholesterol in association with Niemann-Pick disease type C1 (NPC1) and NPC2 proteins that export cholesterol from lysosomes." (PMID 32999035, 2020). "Patients with sporadic FTLD-TDP types A and C and FTLD-tau (Pick’s disease) exhibited similar increases in CatD activity, LAMP-1 and LAMP-2 levels, and lysosomal storage material as patients with FTD-GRN." (PMID 37118844, 2023). "Recently, neuronally derived exosomes in blood were found to contain elevated concentrations of CTSD, LAMP1, and ubiquitinated proteins already at a preclinical stage of AD, compared to controls and subjects with frontotemporal lobar degeneration." (PMID 31521194, 2019).
sarcoma (5 papers, 2013 to 2024). A usually aggressive malignant neoplasm of the soft tissue or bone. "Moreover, in aggressive sarcoma cells, over-sialylation of LAMP1 causes the redistribution of lysosomes to the cell periphery and induces exocytosis of both soluble lysosomal hydrolases and exosomes." (PMID 38474423, 2024). "Sensitization of resistant sarcoma cells was achieved through LAMP1 knockdown, reinstating the function of LAMP1 in promoting lysosomal exocytosis and chemoresistance." (PMID 33297435, 2020). "In pleomorphic and metastatic sarcomas, the downregulation of NEU1 correlates to an increased expression and interaction between LAMP1 and myosin-11, a motor myosin protein, which facilitates lysosome trafficking to the cell periphery and lysosomal exocytosis." (PMID 38474423, 2024).
tuberculosis (5 papers, 2012 to 2025). A chronic, recurrent infection caused by the bacterium Mycobacterium tuberculosis. "We found that LAMP1/2/3 association genes are mainly enriched in Neutrophil degranulation, Tuberculosis, positive regulation of cytokine production and other pathways and terms." (PMID 37603525, 2023). "Indeed, tuberculosis bacilli inhibits fusion of lysosomes with phagosomes through the selective exclusion of the GTPase Rab7 and lysosomal-associated membrane protein 1 (LAMP1) coupled with the retention of Rab5 on the phagosome." (PMID 27005665, 2016). "When TB patients were stratified according to M. tuberculosis genotype, associations were observed between SNPs in LAMP1, MTOR and infection with M. tuberculosis Beijing genotype, but statistical significance was lost after correction for multiple testing." (PMID 22879892, 2012). "After stratification according to M. tuberculosis genotype, we found a suggestive association between TB caused by M. tuberculosis Beijing genotype and a polymorphism in LAMP1, similar to what we have previously shown for polymorphisms in SLC11A/NRAMP1." (PMID 22879892, 2012). "The polymorphism in LAMP1 (rs9577229) showed an association with TB caused by M. tuberculosis Beijing strains, when the TC was combined with the low prevalent TT genotype (p = 0.02)." (PMID 22879892, 2012).
ZIKV infection (5 papers, 2017 to 2022). "ZIKV infection significantly upregulated genes related to lysosomal biosynthesis, including LAMP1 and CLCN7 (lysosomal transmembrane proteins); CSTB and CSTD (lysosomal hydrolases); and ATP6V1C1 and ATP6V0D1 (v-ATPase proteins)." (PMID 36405969, 2022).
asthma (4 papers, 2012 to 2016). "Finally, we noted that, of the 12 vitamin D lung developmental genes transcriptomically related to asthma susceptibility, 4 – LAMP1, PIP5K1B, SCARB2, and TXNIP – were significantly differentially expressed upon administration of vitamin D to cells derived from asthmatic children." (PMID 24188128, 2013). "It was hypothesized that the identified downregulation of M6PR, TPP1, GLB1, NEU1, ACP2, LAMP1 and HGSNAT leads to disorders of lysosome function, which results in asthma by causing T-cell dysfunction." (PMID 25633562, 2015). "As mentioned, 4 of the developmental genes: LAMP1, PIP5K1B, SCARB2 and TXNIP, were differentially expressed in both asthma and upon stimulation of immortalized B-cells derived from asthmatics, suggesting a possible role of these genes in modulating the immune response in asthma." (PMID 24188128, 2013).
ischemia (4 papers, 2018 to 2023). A hypoperfusion of the BLOOD through an organ or tissue caused by a PATHOLOGIC CONSTRICTION or obstruction of its BLOOD VESSELS, or an absence of BLOOD CIRCULATION. "LC3B (red) that colocalized with Lamp1 (green) in the cytoplasm showed autophagy lysosomes, and the images suggested that ischemia and reperfusion activated the significant increases in autophagy lysosome formation (p < 0.05)." (PMID 30018669, 2018). "Treatment with XXMD or CsA markedly downregulated LC3B, Beclin1, and Lamp1 expression after 90 min of ischemia and 24 h of reperfusion compared with the IR group (p < 0.05)." (PMID 30018669, 2018). "We found that, at the early stage of ischemia, OPN expression was enhanced, especially in microglia, and colocalized with LAMP1 and GAL-3, which was accompanied by lysosomal damage, CTSB release, NLRP3 inflammasome activation, and autophagosomes accumulation after HI insult." (PMID 36980197, 2023). "Consistent with previous research, we found that the expression of LAMP-1 did not change significantly after ischemia, but cathepsin D expression was remarkably increased." (PMID 32519067, 2020). "Among the subcellular organelles, there was no merged image of HMGB1 on Rab5, Rab7, LAMP1, LC3A/B, and KDEL indicating that HMGB1 was not imported into the endosomes, phagosomes, lysosome, or endoplasmic reticulum in neurons at 6, 12, and 24 h after ischemia." (PMID 32155899, 2020).
lupus (4 papers, 2015 to 2025). "We investigated neutrophil heterogeneity in patients with systemic lupus erythematosus and identified increased surface levels of LAMP1 (CD107a)." (PMID 40760840, 2025). "The aim of this study was to investigate the role of CD107a (LAMP-1) on cytotoxic CD8+ T-cells in SLE-patients in particular with lupus nephritis." (PMID 33834029, 2021). "Thus, while LAMP1 itself likely does not directly influence lupus pathophysiology, it indicates the increased activation and degranulation of neutrophils and potentially other immune cells, including in inflamed tissues." (PMID 40760840, 2025).
osteosarcoma (4 papers, 2018 to 2024). A usually aggressive malignant bone-forming mesenchymal neoplasm, predominantly affecting adolescents and young adults. "We coexpressed WT or K285T mutant ClC-7 with OSTM1-red fluorescent protein (RFP) in an osteosarcoma U2OS cell line that constitutively expressed LAMP1-GFP to assess the influence of the K285T variant on lysosome morphology." (PMID 38838776, 2024). "In order to analyze lysosomal function, we measured the LAMP1 expression in the osteosarcoma cells with DHA treatment at different time points and concentrations." (PMID 32431605, 2020).
psoriasis (4 papers, 2019 to 2024). An autoimmune condition characterized by red, well-delineated plaques with silvery scales that are usually on the extensor surfaces and scalp. "Few studies have investigated CD107a/lysosomal-associated membrane protein 1 (LAMP-1) in psoriasis." (PMID 37744329, 2023). "Interestingly, in contrast to the keratinocytes of HaCaT with “psoriasis-like” inflammation, LAMP1 was up-regulated in both PP and PN skin, which can be a potential sign of an alternative mechanism of lysosome formation." (PMID 31067781, 2019). "Interestingly, patients with the most pronounced PASI (Psoriasis Area and Severity Index), BSA (Body Surface Area), and DLQI (Dermatology Life Quality Index) scores suffered a high incidence of positive lysosomal-associated membrane protein 1 (LAMP1) expression." (PMID 31067781, 2019). "However, in contrast to our results obtained in skin sections and the data of LAMP1 expression detected in HaCaT cells (Transcripts Per Million, TPM: 298.9), there was down-regulation of LAMP1 in our HaCaT model with “psoriasis-like” inflammation." (PMID 31067781, 2019).
type 2 diabetes (4 papers, 2020 to 2023). "Metformin, the first-line agent in type 2 diabetes treatment, was reported to increase LC3II, p62 and Lysosomal associated membrane protein 1 (LAMP1) expression levels, which further enhanced the level of autophagy." (PMID 36733467, 2023). "However, in type 2 diabetes, lysosomal release, as estimated from the surface LAMP-1 of circulating ordinary platelets, forecasts in vitro WB reactions (lysosomal discharge and αIIbβ3 receptor activity) after ɑ-thrombin provocation (10 U/mL)." (PMID 36924419, 2023). "In conclusion, we found that CML and LamP1 could help us identify subjects with type 2 diabetes with the early stages of DR." (PMID 32344735, 2020).
astrocytoma (3 papers, 2015 to 2023). "In LGG, LAMP1 expression was significantly different among 3 histological subtypes (Astrocytoma vs oligoastrocytoma, P value < .001; Astrocytoma vs Oligodendroglioma, P value < .001; Oligoastrocytoma-vs Oligodendroglioma, P value = .014)." (PMID 37603525, 2023). "In addition, mRNA expressions of LAMP1 were remarkably correlated with histological subtypes, and patients who were in astrocytoma tended to express higher mRNA expression of LAMP1." (PMID 37603525, 2023). "As was shown in Figurer 3, mRNA expressions of LAMP1 and LAMP4 were remarkably correlated with histological subtypes, and patients who were in astrocytoma tended to express higher mRNA expression of LAMPs." (PMID 37603525, 2023).
Burkitt lymphoma (3 papers, 2022 to 2025). A rare form of malignant mature B-cell non-Hodgkin lymphoma. "We stably expressed TMEM192 in Rael Burkitt lymphoma B cells, in which BCAT1 and LAMP1 colocalization was increased by αIgM + CpG stimulation." (PMID 40924473, 2025). "We stably expressed TMEM192 in Rael Burkitt lymphoma Rael B-cells, in which BCAT1 and LAMP1 co-localization was increased by aIgM+CpG stimulation." (PMID 38854072, 2024).
Cerebral ischemia (3 papers, 2018 to 2024). Restriction of arterial blood supply to the brain associated with insufficient oxygenation to support the metabolic requirements of the tissue. "This study suggests that XXMD exerts neuroprotective effects by down-regulating the expression levels of LC3B, Beclin1, and Lamp1 proteins, thereby reducing mitochondrial activation and improving mitochondrial function in cerebral ischemia-reperfusion injury." (PMID 38650626, 2024). "Our previous study demonstrated that that the fluorescence intensity of LC3 and LAMP-1 co-staining were significantly reduced in the penumbral cells, indicating the fusion between autophagosomes and lysosomes was interrupted after cerebral ischemia." (PMID 39155286, 2024). "In addition, XXMD significantly downregulated mitochondrial autophagy and reduced the expression levels of LC3B, Beclin1, and Lamp1 proteins induced by cerebral ischemia-reperfusion." (PMID 38650626, 2024). "Additionally, marked upregulation of the lysosomal marker Lamp1 further supported the notion that mitophagic/lysosomal pathway was activated in cerebral ischemia and reperfusion." (PMID 30018669, 2018). "Moreover, XXMD/CsA notably downregulated mitophagy and reduced the increase in LC3, Beclin1, and Lamp1 expression induced by cerebral ischemia and reperfusion." (PMID 30018669, 2018). "The findings showed that cerebral ischemia and reperfusion resulted in a significant increase in LC3B, Beclin1, and Lamp1 expression compared with the Sham group (p < 0.05)." (PMID 30018669, 2018).
co-infection (3 papers, 2017 to 2022). "Similar to the co-infection assay, the single infection assay revealed that the association of M6-containing phagosomes with the late endosome/lysosome marker LAMP1 is significantly reduced in relation to Anc-containing phagosomes." (PMID 28674418, 2017).
esophageal squamous cell carcinoma (3 papers, 2022 to 2025). Esophageal squamous cell carcinoma (ESCC) is a type of esophageal carcinoma (EC) that can affect any part of the esophagus, but is usually located in the upper or middle third. "Another investigation into the prognostic value of LAMP1 in esophageal squamous cell carcinoma illustrated the correlation of LAMP1 expression with tumor histological differentiation and patients’ prognosis." (PMID 35145930, 2022).
Hyperglycemia (3 papers, 2019 to 2025). An increased concentration of glucose in the blood. "Hyperglycaemia lowered the expression of Tfeb, Lamp1, and Lc3, meaning that autophagy was down‐regulated at the transcriptional (TFEB), lysosomal (Lamp1) and autophagosome assembly (LC3) levels." (PMID 30710421, 2019). "Studies in αTC1-6 cells — a model of α cells — show that, under chronic hyperglycemia, glucagon granules misroute from degradative LAMP2+ lysosomes to LAMP1+ secretory lysosomes, contributing to hypersecretion." (PMID 41026524, 2025). "Moreover, α cells exposed to hyperglycemia showed that glucagon degradation at LAMP2+ lysosomes is reduced, with increased redirection to secretory LAMP1+ lysosomes." (PMID 41026524, 2025).
insulinoma (3 papers, 2019 to 2021). "It has been reported that SPIONs covalently conjugated with antibodies targeting the lysosomal protein marker LAMP1 (LAMP1-SPIONs) rotate in a dynamic magnetic field and cause lysosomal membrane damage in the rat insulinoma tumor cells." (PMID 30791358, 2019).
ischemic stroke (3 papers, 2020 to 2021). A stroke disorder caused by obstruction of blood flow to the brain, due to thrombotic (local blood clot formation) or embolic (due to a blood clot or other material traveling from another site) event. "Moreover, EA treatment at 24 h after ischaemic stroke obviously suppressed the expression of CCAS3, LC3II/I, Beclin1 while increasing the level of P62 and LAMP1 and hence mediating autophagy, which was reversed by RAP." (PMID 33603645, 2021).
pancreatic ductal adenocarcinoma (3 papers, 2019 to 2022). An infiltrating adenocarcinoma that arises from the epithelial cells of the pancreas. "In summary, these results demonstrate that UBL4A inhibits autophagy-mediated proliferation and metastasis of pancreatic ductal adenocarcinoma by directly targeting LAMP1." (PMID 31288830, 2019). "This oncogenic autophagy is also observed in pancreatic ductal adenocarcinoma as suppression of autophagy through the direct interaction between ubiquitin-like protein 4A (UBL4A) and lysosome-associated membrane protein 1 (LAMP-1) inhibits pancreatic tumor migration and invasion." (PMID 33297435, 2020).
renal carcinoma (3 papers, 2018 to 2025). A carcinoma arising from the epithelium of the renal parenchyma or the renal pelvis. "Therefore, LAMP1 emerges as a novel biomarker associated with the diagnosis and prognosis of renal cancer." (PMID 39669571, 2024). "Functional studies on cells have demonstrated the inhibitory effects of LAMP1 on renal cancer cell proliferation, migration, and invasion." (PMID 39669571, 2024). "Our study highlights the potential of LAMP1 as a novel biomarker for diagnosing ccRCC patients and predicting their prognosis, while also providing valuable insights into the underlying molecular mechanisms that could guide targeted therapeutic strategies for renal cancer." (PMID 39669571, 2024). "LAMP1 exerts anti-tumor effects by suppressing the proliferation, migration, and invasion of renal cancer cells." (PMID 39669571, 2024). "Therefore, our study represents the first validation of the novel potential biomarker LAMP1 in ccRCC, which holds promise for its application in diagnosing and prognosticating renal cancer." (PMID 39669571, 2024). "However, experimental evidence suggests that LAMP1 can impede renal cancer cell line proliferation, migration, and invasion." (PMID 39669571, 2024). "However, the specific involvement of LAMP1 in renal carcinoma remains unexplored." (PMID 39669571, 2024). "Furthermore, we have also described the potential mechanism of action of LAMP1 in renal cancer." (PMID 39669571, 2024). "Additionally, we investigated the impact of VHL, a key gene in renal cancer, and LC3C, an autophagy-related gene, on LAMP1 expression through molecular biology experiments to elucidate the potential underlying mechanism." (PMID 39669571, 2024).
renal cell carcinoma (3 papers, 2022 to 2023). "The high expression of ACSS2 in renal cell carcinoma promotes the expression of lysosome-associated membrane protein 1 (LAMP1) to promote tumor proliferation and invasion." (PMID 35740562, 2022). "The knockdown of ACSS2 reduces not only LAMP1 mRNA levels but also LAMP1 protein levels, which in turn leads to the invasion and metastasis of renal cell carcinomas." (PMID 35740562, 2022). "ACSS2 showed no influence on the proliferation and apoptosis of tumor cells, but reduced ACSS2 expression inhibited lysosome-associated membrane protein 1 (LAMP1) protein expression compared with that in the control group, thus preventing the migration and invasion of renal cell carcinoma cells." (PMID 35798917, 2022).
Senile plaques (3 papers, 2023 to 2024). Senile plaques are extracellular deposits of amyloid in the gray matter of the brain. "We found levels of the endolysosomal marker LAMP1 are increased in CA1 and CA3 regions of AD hippocampi, and are enriched around senile plaques, consistent with previous analysis in the AD frontal cortex." (PMID 36825945, 2023).
sialidosis (3 papers, 2020 to 2021). "Similar to other NEU1-deficient models, the expression of LAMP1 was markedly increased in the sialidosis-iNPCs (G227R-iNPCs and V275A/R347Q-iNPCs), compared with the normal-iNPCs." (PMID 33922276, 2021). "While in alpha‐mannosidosis, increased expression of LAMP‐1 was most pronounced in the CD4 and CD8 (T‐cell) compartment, increased LAMP‐1 expression was especially profound in the CD20 (B‐cell) compartment of patients with sialidosis." (PMID 32685355, 2020).
steatosis (3 papers, 2022 to 2023). Increased lipid within the cytoplasm of cells. "The lipophagy-mediated improvement of steatosis was abrogated by inhibition of the fusion of autophagosome and lysosome, and the cell surface expression of the lysosomal protein LAMP1 was upregulated by lipophagy, a common marker of lysosomal exocytosis." (PMID 37443159, 2023). "Furthermore, steatosis hepatocytes secreted sEVs abundant in novel-miR-7 in the circulation, which promotes hyperpermeability of coronary microvascular endothelial cells by directly regulating the lysosomal-associated membrane protein 1 (LAMP1)/Cathepsin B/NLRP3 inflammasome axis." (PMID 37851172, 2023). "In a CMA-deficient model system, the degradation of the coat proteins was inhibited and the association of autophagy proteins and lysosome-associated membrane glycoprotein 1 (LAMP1) with LDs was decreased, resulting in LD accumulation and steatosis." (PMID 35265214, 2022).
amyotrophic lateral sclerosis (2 papers, 2020 to 2021). Amyotrophic lateral sclerosis (ALS) is a neurodegenerative disease characterized by progressive muscular paralysis reflecting degeneration of motor neurons in the primary motor cortex, corticospinal tracts, brainstem and spinal cord. "Interestingly, amyotrophic lateral sclerosis (ALS)-linked mutation in annexin A11 reduced its association with LAMP1-postive compartments in neurons, rendering the formation of more stable and possibly aggregation-prone RNA granules." (PMID 34178987, 2021).
anaphylaxis (2 papers, 2024 to 2025). An acute hypersensitivity reaction that occurs from exposure to an allergen. "The vaccine incorporated lysosomal-associated membrane protein 1 (LAMP1), a protein that directs the plasmid to the lysosomal compartment, reducing the risk of allergen release and anaphylaxis." (PMID 39598421, 2024).